TTF1 (transcription termination factor 1)
Diseases named in the same sentence as TTF1 in open-access papers (continued):
Sharing a sentence is not in itself a finding about the gene and the disease.
lung adenocarcinoma (continued). "Current clinical algorithms for the diagnosis of human lung adenocarcinoma typically require positivity of stains for thyroid transcription factor 1 (TTF-1) and aspartic proteinase Napsin A (NapA), and negativity of stains for either p40 or p63." (PMID 38994972, 2024). "The bronchoalveolar examination showed cancerous cells, identified as non-small cell lung cancer (NSCLC), with positive thyroid transcription factor-1 (TTF-1) expression (i.e., lung adenocarcinoma)." (PMID 39767631, 2024). "The majority of the available data suggest that TTF-1 is favourable prognostic biomarker for lung adenocarcinomas, whereas its role is more conflicting for lung NET." (PMID 37775725, 2024). "Biopsy results of the lung mass were positive for cytokeratin 7 and TTF-1, markers that are highly specific for adenocarcinoma of the lung." (PMID 39070460, 2024). "Per report, IHC showed positive TTF1 and focal p40 staining, consistent with a primary lung adenocarcinoma." (PMID 39544293, 2024). "It has been reported that TTF1 is expressed in ∼90% of small cell lung cancers, ∼60–90% of lung adenocarcinomas and the majority of thyroid carcinomas, but is rarely expressed in other carcinomas." (PMID 38276630, 2024). "Due to its high expression, high specificity and strong sensitivity, TTF-1 is a promising biomarker for tracking lung adenocarcinoma." (PMID 38184620, 2024). "In lung adenocarcinoma, some postulate that TTF-1 seems to promote survival and growth of cancer, but paradoxically, inhibit invasion, metastasis, and progression." (PMID 38994972, 2024). "Napsin A, like TTF‐1, is a useful marker for lung adenocarcinoma and can be useful in differentiating lung cancer from thyroid cancer." (PMID 37261050, 2023). "In terms of histological type, there are few cases with positive TTF‐1 expression in adenocarcinomas derived from organs other than the thyroid gland and lungs, making it highly useful in distinguishing lung adenocarcinoma." (PMID 37261050, 2023). "TTF‐1 is highly useful in differentiating between pancreatic metastasis from lung adenocarcinoma and primary pancreatic cancer, especially when the clinical course and imaging findings are not helpful for differentiating them." (PMID 37261050, 2023). "Immunohistochemistry showed positive expression for thyroid transcription factor‐1 (TTF‐1), a specific marker for the lung, leading to the diagnosis of pancreatic metastasis from lung adenocarcinoma." (PMID 37261050, 2023). "TTF-1, a tissue-specific protein found in thyroid and lung epithelial cells, was tested for its ability to distinguish lung adenocarcinomas from other common adenocarcinomas in 58 body cavity fluid samples." (PMID 37675165, 2023). "Previous studies have shown that TTF-1 positivity in lung adenocarcinoma tissues is a favorable prognostic marker." (PMID 37675165, 2023). "It has been shown that specific markers such as TTF-1 and Napsin A play a crucial role in identifying lung adenocarcinoma in immunohistochemical." (PMID 37780910, 2023). "There was a highly significant relationship between pleural fluid, TTF-1, and lung adenocarcinoma (p=0.000)." (PMID 37675165, 2023). "Lung adenocarcinoma-related markers were evaluated including Thyroid transcription factor-1 (TTF-1) and Napsin A, and ovarian cancer-related markers including pair box gene 8 (Pax-8) and Wilm’s tumor gene 1(WT-1)." (PMID 37337182, 2023). "TTF-1 and napsin A are highly sensitive and specific markers expressed in primary lung adenocarcinoma." (PMID 37198615, 2023). "In the absence of M-MDCs, AT2 cells formed the bulk of the metastatic tumor, which have acquired autonomously a malignant phenotype confirmed by lung adenocarcinoma marker Napsin A and TTF-1." (PMID 37254190, 2023). "MYBPH is a transcriptional target of TTF-1, a master regulator of lung development that plays a role as a lineage-survival oncogene in lung adenocarcinoma development." (PMID 37780567, 2023).
lung adenocarcinoma (continued). "IHC analysis of EGFR and thyroid transcription factor-1 (TTF-1), a sensitive marker of primary lung adenocarcinomas, showed significant enhancement in LC-HFD mice compared with LC-RD mice, which confirmed the H&E results." (PMID 37929799, 2023). "Canine lung cancer organoids recapitulated the tissue architecture of canine lung adenocarcinoma, and expressed TTF1, a lung adenocarcinoma marker." (PMID 37920327, 2023). "An excision biopsy of the uterus showed primary lung adenocarcinoma with immunohistochemistry of TTF-1+." (PMID 37182165, 2023). "Clinically, TTF‐1 expression is commonly used to diagnose the histological type of lung cancer and distinguish primary lung adenocarcinoma from other metastatic adenocarcinomas; additionally, it can be used as a prognostic marker." (PMID 35808895, 2022). "In this case, the immunohistochemical results of CK7, Napsin A and TTF-1 supporting the diagnosis of lung adenocarcinoma were all positive, and the immunohistochemical results of Vimentin, CD10 and PAX-8 supporting the diagnosis of RCCC were all positive." (PMID 35979370, 2022). "CT-guided fine needle biopsy yielded a moderately differentiated thyroid transcription factor 1-(TTF1)-positive NSCLC adenocarcinoma of the lung." (PMID 35448155, 2022). "In our case, the immunohistochemistry staining pattern suggested that the adrenal tumor was most likely a metastasis from lung adenocarcinoma, presenting TTF-1 positivity." (PMID 35915686, 2022). "The HCC827 cell line shows homogeneous staining for the lung adenocarcinoma markers TTF1 and CK7 in both 2D and 3D cultures, reflecting the maintenance of the adenocarcinomatous phenotype." (PMID 35565305, 2022). "TTF-1 is frequently expressed in 3/4 of lung adenocarcinomas and can be used as a tumor origin marker." (PMID 35885495, 2022). "TTF-1 is a marker present in more than 60% of primary lung adenocarcinomas, and is rarely expressed in adenocarcinomas of other origin." (PMID 35885495, 2022). "TTF‐1 is expressed in 69%–80% of cases of lung adenocarcinoma, and the amplification of TTF‐1 has been reported to lead to the proliferation of lung cancer cells." (PMID 35808895, 2022). "We aimed to identify the relationship between thyroid transcription factor‐1 (TTF‐1) expression of lung adenocarcinoma and the efficacy of immune‐checkpoint inhibitor (ICI) therapy." (PMID 35808895, 2022). "Immunostaining with Girdin antibodies confirmed the successful Girdin KO in the tumors from mice transduced with Lenti-sgTrp53-sgGirdin/Cre, and all the tumors were lung adenocarcinomas, based on positive TTF1 staining." (PMID 36428781, 2022). "A total of 50 primary lung adenocarcinoma diagnosed on the basis of cytomorphology and appropriate panel of immunocytochemical markers (TTF1, p40, Napsin A and CK7), were included in the study." (PMID 34514573, 2022). "RNAscope is a more sensitive method than IHC for detecting thyroid transcription factor 1 (TTF-1) and Napsin A expression in primary lung adenocarcinomas." (PMID 35027056, 2022). "As per the preliminary studies, the latency period of two months was able to form lung lesions displaying proliferating cells but by 6 months, mature lung adenocarcinoma was developed which was confirmed by TTF-1 nuclear positivity." (PMID 35892161, 2022). "Right supraclavicular lymph node biopsy was performed, and pathological examination allowed diagnosis of lung adenocarcinoma T2N3M1a, and immunohistochemistry (IHC) revealed the tumor to be NapsinA+, TTF-1+, CK7+, CD10−, and vimentin+." (PMID 34745948, 2021). "Brain metastasis tumors with napsin A and TTF-1 positive are easily classified as lung adenocarcinoma origin." (PMID 33912440, 2021). "The positive expression rates of TTF-1 and NapsinA are higher in lung adenocarcinoma, and TTF-1 is highly specific and sensitive in the diagnosis of adenocarcinoma." (PMID 32282054, 2021).
lung adenocarcinoma (continued). "For example, a combination of TTF-1 (lung and thyroid), galectin-3 (100% in papillary thyroid cancers), and napsin A (lung adenocarcinomas) is used to determine the tumour origin of a lung mass in patients with thyroid nodules." (PMID 33706755, 2021). "The phenotype of squamous cell carcinoma and adenocarcinoma in the primary tumors was faithfully retained in PDX, verified by the staining pattern of the lung adenocarcinoma (LUAD) marker TTF1 and the lung squamous cell carcinoma (LUSC) marker p40." (PMID 34070013, 2021). "It was found that there is a significant amplification on TTF-1 gene locus in lung adenocarcinoma (ADCs), leading to increased proliferation and viability of lung cancer cells." (PMID 34631891, 2021). "In our case series, we described two cases of TC, NOS, one of which showed an aberrant expression of TTF-1, which led to the erroneous diagnosis of lung adenocarcinoma on the biopsy sample." (PMID 34439210, 2021). "Thyroid transcription factor-1 (TTF-1) is mainly expressed in lung adenocarcinomas and regulates angiogenesis activity in the TME." (PMID 34193120, 2021). "Both vascular endothelial growth factor (VEGF) and granulocyte–macrophage colony-stimulating factor (GM-CSF) are regulated by TTF-1, which reprograms lung adenocarcinomas that secrete TME factors in angiogenesis." (PMID 34193120, 2021). "NK2 homeobox 1, also known as thyroid TF-1 (TTF-1), was demonstrated to be frequently suppressed in high-grade lung adenocarcinoma." (PMID 33931584, 2021). "It has been shown that the positive rate of epithelial markers was high in PSCC, while the positive rates of TTF-1 and napsin A which is a marker for lung adenocarcinoma were low." (PMID 34632553, 2021). "Two patients (Cases 2 and 7) were positive for TTF-1 expression, which favoured the diagnosis of lung adenocarcinoma." (PMID 32650830, 2020). "Pulmonary adenocarcinoma generally stains positive for claudin-4, TTF-1, MOC31, CEA, B72.3, BG8, and BER-EP4 markers, with TTF-1 and napsin-A having the highest specificity lung adenocarcinoma." (PMID 33014860, 2020). "Thyroid transcription factor (TTF)-1 expression has been described as a useful marker of primary lung cancer and highly specific for primary lung adenocarcinoma." (PMID 32266605, 2020). "Although Napsin A proved to be more specific and sensitive than TTF1 in lung adenocarcinoma but can it detect poorly differentiated tumors?" (PMID 33247694, 2020). "Thyroid transcription factor‐1 (TTF‐1, encoded by the NKX2‐1 gene) is highly expressed in small‐cell lung carcinoma (SCLC) and lung adenocarcinoma (LADC), but how its functional roles differ between SCLC and LADC remains to be elucidated." (PMID 31782890, 2020). "Our RT-qPCR results show that overexpression of SLFN12 significantly increased TTF-1 mRNA levels in two of the three lung adenocarcinoma cells (HCC827 and H1975)." (PMID 32987632, 2020). "Tumor cells were immunoreactive with TTF1 in eight of eight specimens examined and immunoreactive with Napsin A in six of six specimens examined, confirming a diagnosis of lung adenocarcinoma." (PMID 32333643, 2020). "Elevated in KRAS mutant lung adenocarcinoma with low expression of TTF-1; Seliencing REG4 reduced cancer cell proliferation and tumorigenesis via blocking G2/M transition." (PMID 33489872, 2020). "Although TTF-1 is the predominant marker for lung adenocarcinoma but it has limited sensitivity and specificity." (PMID 33247694, 2020). "Despite considering TTF-1 as the predominant marker for identifying lung adenocarcinoma but it has limited sensitivity and specificity, which means that its expression decreases in relation to the degree of tumor differentiation." (PMID 33247694, 2020). "A remarkable difference in the thyroid transcription factor‐1 (TTF‐1) binding regions on the genome was identified between lung adenocarcinoma (LDAC) and small‐cell lung carcinoma (SCLC)." (PMID 31782890, 2020).
lung adenocarcinoma (continued). "Thyroid transcription factor-1 (TTF-1) is a well-known and routinely used marker by pathologists for the identification of adenocarcinoma of the lung and thyroid cancers." (PMID 32272669, 2020). "TTF‐1 is expressed in 75–80% of lung adenocarcinoma (LADC), a non‐small‐cell lung cancer (NSCLC) subtype, and is a marker of the terminal respiratory unit (TRU) subtype." (PMID 31782890, 2020). "A 65-year-old man, active smoker, was diagnosed with lung adenocarcinoma TTF1+ revealed by a superior vena cava syndrome on mediastinal adenopathy." (PMID 31627742, 2019). "High TTF-1 expression by immunohistochemistry (IHC) has been observed in 70–90% of primary lung adenocarcinomas (ADCs), while almost all squamous cell carcinomas are negative for TTF-1 IHC." (PMID 30736438, 2019). "It was used to eliminate a metastasis in 11.8% of cases, discarding lung adenocarcinoma or thyroid carcinoma (TTF1-), epidermoid carcinoma (p63-), and melanoma (pS100, MelanA, HMB45)." (PMID 31805712, 2019). "A subsequent study showed that TTF-1 overexpression was a favorable prognostic marker among patients with lung adenocarcinoma." (PMID 31196060, 2019). "In lung adenocarcinoma, TTF-1 plays not only an oncogenic role, but also a suppressive role for progression to an invasive condition while maintaining a minimum degree of differentiation paradoxically." (PMID 31196060, 2019). "Previous studies have also demonstrated that TTF-1 positive expression is an important prognostic factor for lung adenocarcinoma." (PMID 31292000, 2019). "Like in our patient, adenocarcinoma of the lung is diagnosed by immunohistochemistry to stain positive for thyroid transcription factor 1 (TTF-1) and/or Napsin A." (PMID 31410343, 2019). "The lung lineage master regulator gene, Thyroid Transcription Factor-1 (TTF-1, also known as NKX2-1), is used as a marker by pathologists to identify lung adenocarcinomas since TTF-1 is expressed in 60 ~ 70% of lung ADs." (PMID 31142791, 2019). "Thyroid transcription factor 1 (TTF1) has been considered a highly sensitive and specific marker for primary lung adenocarcinoma." (PMID 31537838, 2019). "A tissue biopsy demonstrated lung adenocarcinoma that stained positive for TTF-1, and CK7, but was CK5-negative." (PMID 31297337, 2019). "The results of the NG and colleagues study showed that TTF1 was positive in all patients with lung adenocarcinoma (100% specificity)." (PMID 31528168, 2019). "TTF-1-positive lung adenocarcinoma patients had longer overall survival (OS) than those who were TTF-1 negative (19.3 vs. 5.8 months, p < 0.001)." (PMID 31196060, 2019). "A 55-year-old woman, active smoker, diagnosed with a stage IIIB lung adenocarcinoma TTF1+ and ALK−, was treated by cisplatin and vinorelbine with radiotherapy." (PMID 31627742, 2019). "By analyzing data from chromatin immunoprecipitation-based sequencing using antibodies against TTF-1 and SMAD325, we identified TUFT1 as a direct target of transforming growth factor β (TGF-β) which was inhibited by TTF-1 in NCI-H441 lung adenocarcinoma cells." (PMID 29423269, 2018). "Our results indicated CK5/6, p40, and p63 were positive in both P0 and P3 of lung squamous carcinoma LG33 and CK8/18, NapsinA, and TTF-1 were positive in both P0 and P3 of lung adenocarcinoma LG50." (PMID 29788985, 2018). "Nuclear expression of TTF-1 and cytoplasmic expression of Napsin-A are the positive immunohistochemical markers of lung adenocarcinoma." (PMID 29317712, 2018). "Lung adenocarcinoma is positive for TTF-1 which is a homeodomain-containing nuclear transcription protein of the NK2 homeobox (NKX2) gene family, and it plays a crucial role in organogenesis of the thyroid gland and lung." (PMID 30315187, 2018). "When the histological type was known as lung adenocarcinoma or squamous cell carcinoma, the specificity of TTF-1, Napsin-A and p40 were high, but with combined lung adenocarcinoma and squamous cell carcinoma, it remains around or less than 50%." (PMID 29317712, 2018).
lung adenocarcinoma (continued). "With immunostaining all the 28 tumorous tissues showed high level of CK7 and TTF1 expression which confirmed the lung adenocarcinoma diagnosis." (PMID 29415661, 2018). "After scoring the TTF-1 expression for 520 resected lung adenocarcinoma patients, the expression of TTF-1 was correlated with tumor differentiation (p < 0.001)." (PMID 29079814, 2017). "TTF-1 expression is higher in lung adenocarcinoma than in normal lung tissue but decrease in metastatic lesions." (PMID 29079814, 2017). "The expression of TTF-1 was correlated with tumor differentiation in resected lung adenocarcinoma patients (p < 0.001)." (PMID 29079814, 2017). "We, therefore, aimed to clarify the role of TTF-1 in tumor differentiation and the aggressiveness of lung adenocarcinoma." (PMID 29079814, 2017). "The transcription factor Nkx-2/TTF1 has emerged as a candidate regulator of lung adenocarcinoma differentiation and is expressed in 75-85% of human lung adenocarcinomas." (PMID 28177901, 2017). "The expression of TTF-1 in primary lung adenocarcinomas is high but lower than napsin A. TTF-1 expression is rarely positive in cancers of the colon, uterus, ovaries, and so on." (PMID 29124480, 2017). "Currently, TTF-1, detecting in the immunohistochemistry panel, acts as an important prognostic marker for diagnosis of lung adenocarcinoma, which was also proposed by IASLC/ATS/ERS." (PMID 29296178, 2017). "The receptor tyrosine kinase-like orphan receptor 1 (ROR1) sustains prosurvival signalling directly downstream of the lineage-survival oncogene NKX2-1/TTF-1 in lung adenocarcinoma." (PMID 26725982, 2016). "Thyroid transcription factor 1 (Ttf1) was used as a marker for type II epithelial cells, which are precursors for lung adenocarcinoma." (PMID 27494838, 2016). "Previous studies have shown that the patients with positive TTF-1 protein expression can show improvement in lung adenocarcinoma survival." (PMID 27992557, 2016). "Future studies should examine how TTF-1 functions in lung adenocarcinoma-related regulatory and signaling pathways." (PMID 26806377, 2016). "In NSCLC, TTF-1-expression occurs mainly in adenocarcinoma and plays a crucial role in differentiating primary lung adenocarcinoma from pulmonary metastatic disease." (PMID 25889870, 2015). "if both renal cell carcinoma and lung adenocarcinoma are in the differential diagnosis based on morphology and/or clinical history a broad IHC panel including TTF-1, PAX-8 and vimentin should be applied for a definitive diagnosis." (PMID 25889632, 2015). "Recently, development of specific antibodies against p40 (ΔNp63) together with immunohistochemical evaluation of TTF-1 and p40 have made it possible to completely discriminate lung adenocarcinoma and SCC." (PMID 25586059, 2015). "The present study suggested that the combination of MUC5B and TTF-1 expression is useful for discriminating adenocarcinomas from squamous cell carcinomas, yielding prognostic significance in patients with lung adenocarcinoma." (PMID 25733373, 2015). "In the case of breast cancer, ER, PR, GATA3, and mammaglobin can be helpful, while TTF1 and napsin-A can point toward lung adenocarcinoma." (PMID 26106499, 2015). "Consistent with our previous report, TTF-1 positive lung adenocarcinomas developed in EGFRTL/CCSP-rtTA/Cebpb+/+mice as well as in EGFRTL/CCSP-rtTA/Cebpb-/-mice when treated with doxycycline for 10 weeks." (PMID 25767874, 2015). "Thyroid transcription factor-1 (TTF-1) is a peripheral marker of lung adenocarcinoma that is also highly expressed in SCLC." (PMID 26705222, 2015). "Of the 664 lung adenocarcinoma tissue samples, 18 were partially positive for TTF-1 (+−), and 636 were positive for TTF-1 (+) resulting in a total positive rate of 98.49% (+,+−)(including partial positive)." (PMID 24743427, 2014). "Usual type tumor cells of lung adenocarcinoma frequently express TTF-1, Cytokeratin7, Napsin-A, and any of Surfactants." (PMID 24782938, 2014).